CDK4 (cyclin dependent kinase 4)
Diseases named in the same sentence as CDK4 in open-access papers (continued):
Sharing a sentence is not in itself a finding about the gene and the disease.
breast cancer (continued). "We analyzed tissue samples of 63 patients with advanced HR+/HER2- breast cancer treated with endocrine therapy and a CDK4/6 inhibitor." (PMID 36859416, 2023). "As the acquired and intrinsic resistance mechanisms of endocrine therapy drug and CDK4/6 inhibitors is gradually revealed, there is a need to develop novel endocrine drugs with higher efficacy and fewer side effects for breast cancer patients." (PMID 37483519, 2023). "Chemotherapy agents such as Ribociclib, a cyclin-dependent kinase 4 and 6 (CDK4/6) inhibitor, are shown to be effective in breast cancer treatment and improving the survival rate." (PMID 37231064, 2023). "A retrospective evaluation of 288 advanced breast cancer patients (pts) treated with CDK4/6i was performed, and 100 pts also received RT." (PMID 36765648, 2023). "For instance, ID1 promoted lung cancer growth by activating CDK4/cyclin D1 and breast cancer metastasis through S100A9 regulation." (PMID 37759448, 2023). "Herein we will provide preclinical and clinical perspectives on the management of advanced ER+/HER2-breast cancer following progression on combination ET and CDK4/6 inhibitors." (PMID 37035239, 2023). "The modulation of inflammatory cytokine signaling by CDK4 in breast cancer has been revealed using transcriptomic analysis." (PMID 36768557, 2023). "Among these, abemaciclib is the first US Food and Drug Administration (FDA)-approved CDK4/6 inhibitor for adjuvant therapy in HR+ HER2− early-stage breast cancer." (PMID 36849435, 2023). "In this study, we have discovered a novel OGT-MITF-mediated pathway that plays a crucial role in regulating MITF transcriptional activity and conferring resistance to CDK4/6 inhibitors in breast cancer." (PMID 37886470, 2023). "The aim of this retrospective study was to assess the role of [18F]-FDG PET/CT in predicting PFS and OS in breast cancer patients treated with CDK4/6i." (PMID 37519806, 2023). "The impact of CDK4 silencing on sensitivity to palbociclib was also more recently studied in ER+ breast cancer and PDAC models." (PMID 36765923, 2023). "We await results from prospective studies of stereotactic radiation for brain metastases in advanced ER + HER− breast cancer patients treated with CDK4/6i." (PMID 36902831, 2023). "In order to improve ER+ breast cancer treatment, a combination of endocrine therapies with other compounds, such as CDK4/6 inhibitors, mTOR inhibitors, PI3K inhibitors, and AR antagonists, are under investigation." (PMID 37173983, 2023). "PFKFB3 is a hub for coordinating cell cycle and glucose metabolism by binding CDK4 and inhibiting the degradation of CDK4 in breast cancer." (PMID 37253634, 2023). "Ribociclib, a cyclin-dependent kinase 4/6 inhibitor, is a novel targeted therapy for advanced-stage breast cancer." (PMID 37692847, 2023). "We also found that PCK2 promoted cell cycle progression, particularly the G1/S transition, and induced upregulation of E2F1, cyclin D1, cyclin D2, and CDK4 in ER+ breast cancer cells." (PMID 35757841, 2023). "Among 371 advanced breast cancer patients treated with CDK4/6i at our institution, 24 pts (6.5%) received RT to the brain volume before starting CDK4/6i treatment, during this treatment, or just after CDK4/6i completion." (PMID 36902831, 2023). "In this study, we utilized a delta radiomic-based analysis of breast cancer patients with liver metastases on pre- and a few cycles post-treatment CT to predict early treatment response to CDK4/6i therapy." (PMID 37567880, 2023). "In total, data from n = 448 patients who were treated with CDK4/6i at four certified German university breast cancer centers between November 2016 and December 2020 were included in the study." (PMID 36876172, 2023). "This fact can be explained considering the approved therapeutic indications of CDK4/6 inhibitors and considering that breast cancer is much more common in women than in men." (PMID 37895811, 2023).
breast cancer (continued). "Myalgia rate ranged from 5.98 to 20.2% in patients treated with CDK4/6 inhibitors plus ET for early breast cancer which was comparable to myalgia rates reported in the control arms (MonarchE: 5.98% vs. 5.92%; PENELOPE-B: 20.2% vs. 18.5%)." (PMID 37293258, 2023). "Camizestrant, a next-generation oral SERD, shows promise in preclinical models of ER+ breast cancer alone and in combination with CDK4/6 and PI3K/AKT/mTOR inhibitors to address endocrine resistance, a current barrier to treatment." (PMID 37725704, 2023). "One attempt of treatment escalation in ER+/HER2- early breast cancer has been to combine adjuvant endocrine therapy with CDK4/6 inhibitors." (PMID 36950554, 2023). "Studies indicate that approximately 20% of HR + breast cancer treated with CDK4/6i experience primary resistance, while over 30% of patients develop secondary resistance." (PMID 37475713, 2023). "For example, The US Food and Drug Administration has authorized the CDK4/6 inhibitor palbociclib, which is used to treat breast cancer." (PMID 36865574, 2023). "It has been well established that miR-34a is downregulated in breast cancer and plays a key role in regulating genes involved in the cell cycle, such as cyclin-dependent kinase 4 (CDK4) and CDK6, as well as BCL2, which participates in apoptotic mechanisms." (PMID 37576994, 2023). "The combination of CDK4/6 inhibitors + fulvestrant or tamoxifen effectively prolongs survival in patients with estrogen receptor-positive (ER+) breast cancer." (PMID 37627092, 2023). "We selected patients diagnosed with endocrine-receptor-positive and HER2-negative breast cancer who were treated with all three CDK4/6i as first-line therapy at a reference center." (PMID 37239834, 2023). "Because the patient had advanced breast cancer and had undergone gastrointestinal palliative surgery, endocrine therapy with CDK4/6 inhibitors in combination with exemestane was selected after a multidisciplinary consultation." (PMID 36966290, 2023). "Hormone receptor-positive, HER2-negative advanced breast cancers exhibit high sensitivity to CDK4/6 inhibitors such as palbociclib." (PMID 37330596, 2023). "The combination of CDK4/6 inhibitors with endocrine therapy in advanced HR+/HER2− breast cancer is the mainstay of the initial therapy of this disease." (PMID 36765648, 2023). "In predominantly CDK4-dependent cells (such as estrogen receptor-positive [ER+] breast cancer), abemaciclib, ribociclib, and palbociclib displace p21 from the CDK4/cyclin D1 complex (but not CDK6 from CDK6/cyclin D1)." (PMID 37369022, 2023). "Based on our results, we propose Pak1 inhibitors combined with ET and CDK4/6 inhibitors as a possible approach for the treatment of ER+ resistant breast cancers." (PMID 37258566, 2023). "CDK4/6 inhibitor in combination with endocrine therapy is highly effective treatment for HR+ breast cancer." (PMID 38017459, 2023). "This study not only unveils a novel mechanism governing resistance to CDK4/6i but also offers a potential avenue for the future treatment of resistant breast cancer patients." (PMID 37886470, 2023). "CDK4/6 and aromatase are prominent targets for breast cancer drug discovery and are involved in abnormal cell proliferation and growth." (PMID 36985460, 2023). "We conducted a prospective, single-center study of patients with breast cancer treated with CDK4/6i who received mRNA-1273 vaccination, as well as a comparative group of healthcare workers." (PMID 37046661, 2023). "We retrospectively evaluate the results of patients (pts) with advanced breast cancer treated at our institution with CDK4/6i and radiotherapy to the brain." (PMID 36902831, 2023). "Although CDK4/6 inhibitors for breast cancer have achieved remarkable clinical success, the specific mechanisms of how CDK4 and CDK6 affect tumor micro-environment (TME) and anti-tumor immunity are still poorly understood." (PMID 37833461, 2023).
breast cancer (continued). "The phase II MAINTAIN trial enrolled patients with advanced ER+/HER2-breast cancer who progressed on ET and a CDK4/6 inhibitor, of whom 84% received prior palbociclib." (PMID 37035239, 2023). "Few data are available about the immune response to mRNA SARS-CoV-2 vaccines in patients with breast cancer receiving cyclin-dependent kinase 4/6 inhibitors (CDK4/6i)." (PMID 37046661, 2023). "Although treatment with hormone and CDK4/6 inhibitors is successful in luminal breast cancer, resistance to these treatments is frequent, highlighting the need for novel therapeutic strategies to delay disease progression and improve patient survival." (PMID 36792625, 2023). "A recent study suggests that CDK6-deficient cancer cells that rely on the function of CDK4 in cell cycle progression are sensitive to these inhibitors; in contrast, upregulation of CDK6 in breast cancer cells promotes CDK4/6 inhibitor resistance." (PMID 37744274, 2023). "Our clinical studies contribute crucial evidence to support the proposition that MITF-mediated pathways are pivotal in orchestrating resistance to CDK4/6i among breast cancer patients." (PMID 37886470, 2023). "Based on eventual development of CDK4/6 inhibitor resistance and there being no approved therapies to overcome the resistance, we established a preclinical model with palbociclib-resistant breast cancer to reveal mechanisms of CDK4/6 inhibitor resistance." (PMID 38017459, 2023). "In fact, the use of CDK4/6 inhibitors in combination with AIs or fulvestrant is now being suggested as the standard therapy for ER+ advanced breast cancer patients." (PMID 37173983, 2023). "To the best of our knowledge, we reported the biggest case series of cAEs occurring in breast cancer patients treated with all the CDK4/6i treatments available." (PMID 37509319, 2023). "The approval of CDK4/6 inhibitors has dramatically improved care for the treatment of HR+/HER2– advanced breast cancer, but navigating the rapidly-expanding treatment evidence base is challenging." (PMID 37366894, 2023). "All in all, we believe that the paradigm of HR+/HER2− advanced breast cancer was completely changed for the better in the last decade with the introduction of CDK4/6is, and we are looking forward to seeing what the future brings for these inhibitors." (PMID 37759823, 2023). "It is recognized that CDK4/6 inhibitors promote autophagy in various cancer models, including breast cancer." (PMID 37190065, 2023). "In Module 2A, 31 patients with post-CDK4/6 inhibitor HR+/HER2− advanced breast cancer received samuraciclib in combination with fulvestrant: 6 at 240 mg OD and 25 at 360 mg OD of samuraciclib." (PMID 37488191, 2023). "Inhibitors of cyclin‐dependent kinase 4 and 6 (CDK4/6) are targeted therapeutic drugs for breast cancer treatment." (PMID 36825764, 2023). "In line with the existing literature data, we found alopecia as a very frequently reported cAE, probably due to the synergetic effect between CDK4/6i and ET which are prescribed in combination for breast cancer treatment." (PMID 37509319, 2023). "The standard of care for ER+ breast cancer involves estrogen antagonists such as tamoxifen or fulvestrant in combination with CDK4/6 inhibitors such as palbociclib." (PMID 37627092, 2023). "Resistance to endocrine treatments and CDK4/6 inhibitors is considered a near-inevitability in most patients with estrogen receptor positive breast cancers (ER + BC)." (PMID 37452026, 2023). "Selective CDK4/6 inhibitors (CDK4/6i) act by blocking the cyclin D1/CDK4/6 complex and inhibit cell cycle transition and thus, cancer cell proliferation as well as endocrine resistance in breast carcinoma." (PMID 37509319, 2023). "Patients with estrogen receptor positive breast cancer (ER + BC) treated with palbociclib (CDK4/6 inhibitor) frequently develop resistance." (PMID 37452026, 2023).
breast cancer (continued). "Cyclin D1 is required for the proliferation of mammary epithelial cells during pregnancy, and the knockout of either cyclin D1 or CDK4 prevents the development and growth of mammary carcinomas arising from luminal epithelial cells in mice." (PMID 37835528, 2023). "This demonstrated that prolonged CDK4/6 inhibition in breast cancer lines prevented and delayed mitotic entry, as expected if cell cycle progression was defective." (PMID 35037284, 2022). "ERBB2 mutations were identified in 5/41 CDK4/6-resistant tumor, and preclinical work demonstrated that ERBB2 mutation activates downstream MAPK/AKT/mTOR and confers resistance to CDK4/6 blockade in breast cancer cells." (PMID 35804935, 2022). "Herein, we show that upregulation of CDK6, p-CDK2, and/or cyclin E1 is associated with adaptation and resistance to AI-monotherapy and combined CDK4/6i and ET in ER+ advanced breast cancer." (PMID 36153348, 2022). "Acquired CDK6 amplification has been found to promote breast cancer resistance to CDK4/6 inhibitors." (PMID 35463324, 2022). "While such mutations are common in solid tumors, to date, regulatory approval of CDK4/6 inhibitors has only been granted for the treatment of hormone receptor-positive (HR+)/human epidermal growth factor receptor 2-negative (HER–) breast cancer." (PMID 36291780, 2022). "The ablation of PTEN, through increased AKT activation, was sufficient to promote resistance to CDK4/6 inhibition in breast cancer cells in vitro and in vivo." (PMID 35804935, 2022). "Here, we review the published literature with regard to the rationale for CDK4/6-directed therapies in HER2+ breast cancer." (PMID 35742993, 2022). "Fortunately, the expression of androgen receptor (AR) is positively correlated with RB, which promotes cyclin D activation, suggesting that CDK4/6 inhibitors have great potential in the treatment of HER2-negative breast cancer with AR-positive." (PMID 35311116, 2022). "CDK4/6 inhibitors have changed the treatment strategy for HR+/HER2− advanced breast cancer patients, and more than 17 CDK4/6 inhibitors in combination with various drugs, are now being tested or have been tested in clinical trials." (PMID 35938171, 2022). "More recently, a combination of JQ1 and the CDK4/6 inhibitor palbociclib has been found to synergistically inhibit cell growth through induction of cell cycle arrest in TN breast cancer cell lines." (PMID 36224576, 2022). "The 10 most frequent words in Web of Science were resistance, breast cancer, palbociclib, expression, cdk4, combination, cancer, abemaciclib, therapy, and apoptosis." (PMID 36530984, 2022). "We recently reported that CDK4/6 inhibitors can induce similar changes in luminal breast cancer cells, both in vitro and in vivo (including in clinical specimens)." (PMID 35248122, 2022). "Targets including BCL2, CDK4 and MCL1 were highly expressed in all tumors; MCL1 was significantly increased in breast cancer and lung adenocarcinoma and CDK4 in colon adenocarcinoma." (PMID 35249548, 2022). "Despite the effectiveness of CDK4/6 inhibitors in HR+ breast cancer, their preclinical and clinical effectiveness has been limited in other predominantly RB-proficient tumor types, such as in NSCLC, colorectal cancer and melanoma." (PMID 36051751, 2022). "For instance, treatment of 22 breast cancer patients with a CDK4/6 inhibitor has resulted in complete response in one patient, partial response in 8 patients, and stable disease in 13 patients." (PMID 36266723, 2022). "Due to the efficacy, safety and tolerability of the CDK4/6 inhibitors in HR+ breast cancer, and multiple nodes of oncogenic signals converging on CDK4/6 in multiple cancer types, there has been significant interest in extending their use to other cancer types." (PMID 36067171, 2022). "This work and others have led to the current Phase Ib clinical trial on assessing the efficacy of a combination treatment of an Akt inhibitor and CDK4/6 inhibitor on breast cancer." (PMID 36291790, 2022).
breast cancer (continued). "Inhibitors of cdk4/6 are promising cancer therapeutics, and several of these inhibitors are currently used to treat breast cancer." (PMID 36091143, 2022). "When studding the presence of these targets we observed that BCL2 was highly expressed in lung and breast cancer and CDK4 in breast and prostate." (PMID 35249548, 2022). "Understanding the mechanism of the resistance to CDK4/6i is critical for personalized treatment in breast cancer." (PMID 35804935, 2022). "With the development of breast cancer therapy, the clinical application of abemaciclib has been considered a commonly used means due to its significant inhibitory effect on CDK4 and CDK6." (PMID 36226863, 2022). "The combination of CDK4/6 inhibitors and endocrine therapy is now considered the standard of care for patients with estrogen receptor-positive (ER+) breast cancer." (PMID 35740538, 2022). "The addition of cyclin-dependent kinase 4/6 (CDK4/6) inhibitors to regimens for advanced ER+ breast cancer is one of the most significant advances in the last decade." (PMID 35740538, 2022). "WEE1 is targeted to inhibit the growth of breast cancer cells resistant to endocrine therapy and CDK4/6 inhibitors." (PMID 36358806, 2022). "For nearly two decades, CDK4/6 inhibitors have become the standard of care for HR+/HER2- breast cancer." (PMID 35800379, 2022). "Similar findings of a need for regular treatment strategy review were identified in targeted CDK therapies for breast cancer patients with metastases utilizing CDK4/6 inhibitors." (PMID 36507516, 2022). "CDK4 gene amplification has been found in numerous types of cancer including breast cancer, sarcoma, cervical cancer, and melanoma." (PMID 35686110, 2022). "Among the various mechanisms mediating drug resistance to CDK4/6 inhibitors found in HR‐positive/HER2‐negative breast cancer cells, upregulation of the PI3K/mTOR pathway is a very common one, making it a potential target for reversal of drug resistance." (PMID 38089455, 2022). "MCL1 was significantly increased in breast cancer and lung adenocarcinoma, and CDK4 in colon adenocarcinoma." (PMID 35249548, 2022). "To date, three selective CDK4/6 small inhibitors have been introduced in the clinic for the treatment of hormone positive advanced breast cancer patients, following the impressive results obtained in phase III clinical trials." (PMID 35712501, 2022). "Currently, the CDK4 inhibitor Palbociclib has been used in the clinical treatment of breast cancer with a longer progression-free survival (PFS) than that in the control group." (PMID 35494047, 2022). "Some chemotherapeutics possess anti-cancer efficacy via inducing cellular senescence, such as Palbociclib, a specific CDK4/6 inhibitor, which was approved in 2015 for clinical treatment of advanced breast cancer." (PMID 35078476, 2022). "Another family of newly developed anti-cancer drugs, the CDK4/6 inhibitors (CDK4/6i), are effective in breast cancer treatment, and these inhibitors are actively being tested and expanded in other malignancies." (PMID 36185294, 2022). "One common theme is a rebound increase in activity of upstream pathways (such as the PI3K pathway) in luminal breast cancer cells treated with CDK4/6i." (PMID 35248122, 2022). "Overall, epigenetic profiling of cfDNA has many potential benefits that have gone mostly unexplored in the context of breast cancer resistance to CDK4/6 inhibitors." (PMID 36176758, 2022). "We propose that inactivation of E-cadherin, a lobular histology, and cytosolic Id2, should be considered as criteria to include ERNEG and HER2POS ILC patients for clinical CDK4/6 breast cancer intervention trials." (PMID 35437308, 2022). "Such as Cyclin-Dependent Kinase 4/6 (CDK4/6) Inhibitors which have been shown to have a promising clinical outcomes in breast cancer." (PMID 35713387, 2022).